ANKRD30BP2 (ANKRD30B pseudogene 2)
Synonyms: CT85; CTSP-1; formerly C21orf99
Gene: Transcribed unprocessed pseudogene on chromosome 21 (13,038,208 to 13,067,033, forward strand). Ensembl gene ENSG00000224309.
Diseases named in the same sentence as ANKRD30BP2 in open-access papers:
ANKRD30BP2 is named in the same sentence as 3 diseases in open-access papers, as found by Europe PMC text mining. Sharing a sentence is not in itself a finding about the gene and the disease.
ANKRD30BP2 shares sentences with these, for which no sentence is quoted: bladder cancer (1 paper); cancer (1); lung adenocarcinoma (1).